HNRNPF (heterogeneous nuclear ribonucleoprotein F)
Description:
Component of the heterogeneous nuclear ribonucleoprotein (hnRNP) complexes which provide the substrate for the processing events that pre-mRNAs undergo before becoming functional, translatable mRNAs in the cytoplasm. Plays a role in the regulation of alternative splicing events. Binds G-rich sequences in pre-mRNAs and keeps target RNA in an unfolded state.
Synonyms: HNRPF; OK/SW-cl.23; mcs94-1
Tractability: Small molecule: a structure with a bound ligand is known. Antibody: its Gene Ontology location is reachable by antibodies, with high confidence. PROTAC: UniProt records ubiquitination sites on it; ubiquitination databases record sites on it; its protein half-life has been measured.
Gene: Protein-coding gene on chromosome 10 (43,385,617 to 43,409,523, reverse strand). Ensembl gene ENSG00000169813.
Subcellular location: Nucleus, nucleoplasm
Subcellular location (Human Protein Atlas): Nucleoplasm
Pathways (Reactome):
Metabolism of RNA: Processing of Capped Intron-Containing Pre-mRNA; mRNA Polyadenylation; mRNA Splicing - Major Pathway
Disease: Dengue Virus-Host Interactions
Immune System: Gene and protein expression by JAK-STAT signaling after Interleukin-12 stimulation
Signal Transduction: FGFR2 alternative splicing
Gene Ontology:
Molecular function: protein binding; RNA binding; single-stranded RNA binding; nucleic acid binding
Biological process: regulation of RNA splicing; mRNA splicing, via spliceosome; RNA processing
Cellular component: catalytic step 2 spliceosome; membrane; nucleoplasm; nucleus; plasma membrane; ribonucleoprotein complex; synapse
Genetic constraint (gnomAD): Loss-of-function variants: 2 observed, 27.05 expected, observed/expected ratio (o/e) 0.0739, 90% interval 0.029 to 0.23. The upper end of that interval is the gene's LOEUF score, 0.23, which puts it in group 1 of 6, group 1 being the genes least tolerant of losing a copy. Missense variants: 299 observed, 567.03 expected, observed/expected ratio (o/e) 0.53, 90% interval 0.48 to 0.58. Synonymous variants: 234 observed, 222.71 expected, observed/expected ratio (o/e) 1.05, 90% interval 0.94 to 1.17.
Homologues: Orthologues: chimpanzee HNRNPF (100% identical), macaque HNRNPF (100% identical), mouse Hnrnpf (98% identical), rat Hnrnpf (98% identical), dog HNRNPF (98% identical), guinea pig HNRNPF (98% identical), Drosophila melanogaster glo (36% identical), Drosophila melanogaster fus (24% identical), Caenorhabditis elegans sym-2 (24% identical), Caenorhabditis elegans rbm-12 (15% identical), Caenorhabditis elegans hrpf-2 (14% identical). Paralogues in human: HNRNPH1 (77% identical), HNRNPH2 (75% identical), HNRNPH3 (47% identical), GRSF1 (36% identical), ESRP1 (30% identical), ESRP2 (27% identical), RBM12B (22% identical), RBM12 (20% identical).
Diseases named in the same sentence as HNRNPF in open-access papers:
HNRNPF is named in the same sentence as 31 diseases in open-access papers, as found by Europe PMC text mining. Sharing a sentence is not in itself a finding about the gene and the disease. The quoted sentences say what the papers report.
breast carcinoma (9 papers, 2013 to 2026). "To study the function of HnRNPF in breast cancer, we analyzed the top 1000 genes highly correlated with HnRNPF using the Metascape website for functional enrichment analysis." (PMID 41492473, 2026). "Depletion of USP30-AS1 enhanced the interaction between HnRNPF and p21 mRNA, increasing p21 mRNA stability and ultimately inhibiting breast cancer cell proliferation." (PMID 41492473, 2026). "Our data demonstrated that USP30-AS1 plays an oncogenic function in breast cancer through HnRNPF/p21 and EZH2/c-Myc/p21 axes." (PMID 41492473, 2026). "Our previous study reported the upregulation and oncogenic role of USP30-AS1 in breast cancer via the HnRNPF/p21 and EZH2/c-Myc/p21 axes." (PMID 41614739, 2025). "Autoantibodies were significantly higher in breast cancer patients relative to controls (P < 0.01), with an AUC of 0.73 and 0.69 for hnRNPF and FTH1 autoantibodies, respectively." (PMID 25143958, 2014). "Additionally, HnRNPF can inhibit the migration and invasion of breast cancer cells, and patients with higher HnRNPF expression exhibited a better prognosis." (PMID 41492473, 2026). "Conversely, exogenous HnRNPF increased p21 expression in breast cancer cells." (PMID 41492473, 2026). "Moreover, hnRNPF has been shown to regulate cell proliferation via S6K2 in breast cancer cell lines." (PMID 25284964, 2013). "Together, these findings demonstrate the critical role of USP30-AS1 in breast cancer progression through HnRNPF/p21 and EZH2/c-Myc/p21 axes, highlighting its potential as a therapeutic target for breast cancer treatment." (PMID 41492473, 2026). "For example, a HIF-1α anti-sense lncRNA, HIFAL introduces the PKM2/PHD3 complex into the nucleus by binding to heterogeneous nuclear ribonucleoprotein F (hnRNPF) to enhance the production of hypoxia-inducible factor-1 (HIF-1) and promote breast cancer." (PMID 39539540, 2024). "Additionally, hnRNPC and hnRNPF enhanced cell survival and EMT in breast cancer and bladder cancer by controlling the stabilization of mRNAs, and the detection of hnRNPC suggests a negative prognosis in oral squamous carcinoma patients." (PMID 35875075, 2022).
bladder cancer (7 papers, 2020 to 2024). "HNRNPF increases the stability of Snail1 mRNA and promotes the epithelial–mesenchymal transition of bladder cancer cells." (PMID 33542193, 2021). "Our previous study showed that heterogeneous nuclear ribonucleoprotein F (hnRNP-F) could induce epithelial-mesenchymal transition and metastasis in bladder cancer (BC), however, the role and mechanism of hnRNP-F in mediating the proliferative ability of BC cells remain unclear." (PMID 33391425, 2021). "In addition, heterogeneous nuclear ribonucleoprotein F, by regulating the TPX2 protein, promotes the cell cycle and proliferation of bladder cancer cells." (PMID 35806060, 2022). "Since the roles of HNRNPF and HNRNPA2B have been investigated in bladder cancer before, while the roles of PUF60 in the development and progression of bladder cancer remains unclear, we set off to investigate the roles and functions of PUF60 in bladder cancer." (PMID 33117697, 2020).
prostate carcinoma (6 papers, 2019 to 2025). A carcinoma that arises from epithelial cells of the prostate gland. "This interplay between LTFe and HNRNPF highlights the pivotal roles of eRNA and RBPs in modulating gene expression through chromatin architecture, providing important insights into the molecular mechanisms driving prostate cancer progression." (PMID 40082405, 2025). "Furthermore, studies have implicated members of the HNRNPF/H RBP family, particularly HNRNPH1, in the pathogenesis of multiple cancer types, including mantle cell lymphoma, Burkitt lymphoma, prostate cancer and Ewing sarcoma (EWS)." (PMID 40766465, 2025). "Indeed, JMJD1A was reported to be involved in the splicing of AR-V7 in prostate cancer cells; mechanistically, HNRNPF was shown to interact with JMJD1A to promote this splicing event." (PMID 30939845, 2019). "In the present study, we showed that HNRNPF is significantly overexpressed in prostate tumor tissues, and data from the TCGA indicated that HNRNPF expression is closely related to the clinical progression of PCa, suggesting that HNRNPF plays a tumorigenic role in prostate cancer." (PMID 39567496, 2024). "RASSF2, which is a tumor-suppressor in the prostate cancer mouse model, might be coregulated by FXR1, FXR2, HNRNPA1, PTBP1, G3BP1, HNRNPF, and SRSF7." (PMID 32316190, 2020).
thyroid cancer (4 papers, 2021 to 2024). "supported the idea that the hsa-miR-139-5p/HNRNPF axis served as a novel regulatory mechanism associated with the modulation of major thyroid cancer signaling pathways and tumor virulence." (PMID 35651807, 2022). "The miR139-5p is a prognostic thyroid cancer marker involved in HNRNPF-mediated alternative splicing." (PMID 39578854, 2024). "In thyroid cancer, alternative splicing mediated by HNRNPF can contribute to conventional cancer-related pathways including RTK/RAS/MAPK and PI3K/AKT/MTOR signaling." (PMID 37968457, 2023).
diabetes (2 papers, 2015 to 2023). "Moreover, HNRNPF has been suggested to be a potential target for the treatment of hypertension and kidney injury in diabetes." (PMID 36769128, 2023).
Hypertension (2 papers, 2018 to 2023). The presence of chronic increased pressure in the systemic arterial system. "Heterogeneous nuclear ribonucleoprotein F has been shown to protect against hypertension, renal hypertrophy, and interstitial fibrosis in a diabetic mouse model." (PMID 30419808, 2018).
lung carcinoma (2 papers, 2023 to 2025). "Among these genes, the genes that contributed the most to necroptosis and ICD-related risk models including necroptosis-related gene “HNRNPF” and ICD-related gene “FGF2”, respectively, were selected and performed in vitro experiments to verify the function of lung cancer." (PMID 37968457, 2023). "The results of the CCK-8 assay and EDU assay proved that the knockdown of HNRNPF and FGF2 obviously inhibited lung cancer cells proliferation." (PMID 37968457, 2023). "We next determined the expression levels of HNRNPF and FGF2 in HBE and different lung cancer cell lines." (PMID 37968457, 2023). "In vitro assay showed that HNRNPF and FGF2 promoted lung cancer cell proliferation and migration and were also involved in cell death." (PMID 37968457, 2023). "The knockdown of HNRNPF and FGF2 inhibited the proliferation and migration of lung cancer cells." (PMID 37968457, 2023).
Alzheimer disease (1 paper, 2013). A progressive, neurodegenerative disease characterized by loss of function and death of nerve cells in several areas of the brain leading to loss of cognitive function such as memory and language. "HNRNPF is involved in multiple regulatory pathways, and it has been associated with late onset Alzheimer disease, modulate neuronal viability, and is also reported to be associated with cancers." (PMID 24478790, 2013).
carcinoid tumor of the lung (1 paper, 2013). "Compared to the carcinoid tumor of the lung, significantly increased expression of LDHB and hnRNPF was found in 16/16 and 11/16 fresh MCC tumors, respectively." (PMID 25284964, 2013).
esophageal cancer (1 paper, 2024). A primary or metastatic malignant neoplasm involving the esophagus. "In the other clusters, the genes SCML4, HNRNPF, IFRD1, CSTA, ABL1, etc., have a causal relationship with esophageal cancer." (PMID 38434988, 2024). "Similarly, genes like SCML4, HNRNPF, IFRD1, CSTA, ABL1 in other immune cell clusters also exhibit a causal relationship with esophageal cancer." (PMID 38434988, 2024).
oral cancer (1 paper, 2022). "This study demonstrated the pro-tumor roles of CCL13 in oral cancer and illustrated that stress granules appeared to a positive regulator of CCL13 expression in M2 TAMs via improving the DDX3Y/hnRNPF-mediated mRNA stability of CCL13." (PMID 36291863, 2022).
Rett syndrome (1 paper, 2021). A severe neurodevelopmental disorder affecting the central nervous system. "However, HNRNPF, an ortholog of sym-2, is associated with the neurodevelopmental disorder Rett syndrome, suggesting that HNRNPF has an important role in preserving neuronal integrity." (PMID 33554054, 2021).
schizophrenia (1 paper, 2022). A major psychotic disorder characterized by abnormalities in the perception or expression of reality. "Some proteins of the snRNP complex, the core component of the splicing operation, such as heterogeneous nuclear ribonucleoproteins L (HNRNPL), F (HNRNPF), and A2/B1 (HNRNPA2), along with heat shock 70 kDa protein 4L (HSPA4L), were found upregulated in the schizophrenia-derived organoids." (PMID 36451159, 2022).
type 1 diabetes (1 paper, 2015). "We investigated whether heterogeneous nuclear ribonucleoprotein F (hnRNP F) stimulates renal ACE-2 expression and prevents TGF-β1 signalling, TGF-β1 inhibition of Ace-2 gene expression and induction of tubulo-fibrosis in an Akita mouse model of type 1 diabetes." (PMID 26232095, 2015).
tumor (19 papers, 2013 to 2025). "Deletion of a single SE associated with HNRNPF was sufficient to result in a >80% reduction of tumor growth." (PMID 37673892, 2023). "HNRNPF expression was detected in ten pairs of PCa tumor tissues and matched normal tissues, and the results showed a dramatic increase in HNRNPF expression in PCa tumors." (PMID 39567496, 2024). "To establish a functional role for this SE in driving HNRNPF expression and consequently tumor growth, we deleted ~1800 bases spanning the 5′ distal enhancer in the human MIA PaCa-2 PDAC cell line." (PMID 37673892, 2023). "In combination, these findings support a functional role for SE-regulated HNRNPF expression in vivo, in tumor growth." (PMID 37673892, 2023). "Additional analyses showed that HRAS exon 5 PSI is positively correlated with HNRNPH1 gene expression across tumor types and negatively correlated with HNRNPF expression." (PMID 37399401, 2023). "Notably, like LTF, HNRNPF exhibited low expression levels in cancer, further highlighting a potential regulatory mechanism within the tumor context." (PMID 40082405, 2025). "In contrast, HNRNPF exhibited a positive correlation with MYC activation in almost all tumor types." (PMID 37399401, 2023). "hnRNPF was an RNA binding protein correlating with tumor progression." (PMID 36291863, 2022). "ANKRD40, HNRNPF, IQGAP2, OTUD7B, and THAP5 mutations were detected in 1 tumor, each." (PMID 24223926, 2013). "From these RBPs, only HNRNPH1 is differentially expressed between tumor core and peripheral neoplastic cells, while four RBPs (HNRNPH1, HNRNPF, TRA2A, DDX42) are reported to be differentially spliced themselves." (PMID 39936571, 2025). "The results showed that the expression of HNRNPF and FGF2 was elevated in the majority of tumor tissues (T) compared with the matched adjacent non-tumor tissues (N)." (PMID 37968457, 2023). "Corroborating these results, analysis of publicly available human single cell (sc)RNA-seq data showed that HNRNPF is also upregulated at the RNA level in PDAC cells compared to normal ducts and that its expression increases with tumor stage." (PMID 37673892, 2023). "Our 2D-PAGE revealed some fragments to be upregulated while 1D-WB showed upregulation of HNRNPF and perturbation of HNRNPH1/2 in the central as well as in the peripheral part of the tumor." (PMID 34563043, 2021). "Taking advantage of two primary human MCC cells lines established in our laboratory as well as fresh MCC tumor samples, we measured the expression of LDHB and hnRNPF at the mRNA level." (PMID 25284964, 2013). "Notably, iCAFs marked by TPM2 were enriched in the initial differentiation phase while myCAFs characterized by BIRC3, CCT6A, HNRNPF, and ID1 were enriched in the terminal differentiation phase during tumor progression." (PMID 37968457, 2023). "Proteins that were perturbed in expression level in the peripheral or in the central part of the tumor as compared with the non-involved part included S100A11, HNRNPF, HNRNPH1 or HNRNPH2, GSTP1, PKM and FABP1." (PMID 34563043, 2021).
cancer (15 papers, 2013 to 2025). A tumor composed of atypical neoplastic, often pleomorphic cells that invade other tissues. "HNRNPF contributes to cancer progression by regulating the splicing of oncogenic transcripts, such as the macrophage-stimulating 1 receptor (MST1R), leading to the activation of downstream signaling pathways implicated in tumorigenesis." (PMID 40724932, 2025). "Indeed, given this correlation and the fact that HNRNPF has been shown to be upregulated in other cancers, we find that the H3K27Ac signal at the HNRNPF SE is higher in cancer cells compared to normal cells and tissues." (PMID 37673892, 2023). "Heterogeneous nuclear ribonucleoprotein F (hnRNPF), a member of the hnRNP family, is involved in gene expression and signal transduction, playing significant roles in several types of cancer, including GC." (PMID 37865686, 2023). "We previously analyzed the expression levels of HNRNPF and HNRNPH1 or HNRNPH2 on normal and several types of cancer tissues." (PMID 34563043, 2021). "Even though we identified the HNRNPF SE as a driver of PDAC, the H3K37Ac signal at this locus is elevated in other cancer types compared to normal tissues, suggesting that this pathway is aberrantly activated in other cancers as well." (PMID 37673892, 2023). "Based on these findings, we hypothesized that SE regulation of HNRNPF is a key driver of PDAC growth and that it likely plays a role in other cancers." (PMID 37673892, 2023). "HNRNPs participated in cancer‐related pathways including protein secretion, mitotic spindle, G2/M checkpoint, DNA repair, IL6/JAK/STAT3 signal and coagulation, of which hnRNP genes of HNRNPF, HNRNPH2, HNRNPU and HNRNPUL1 are more likely to be implicated." (PMID 32915499, 2020). "Consistent with previous findings in other types of human cancer, reduced LDHB and hnRNPF expressions were observedboth at the mRNA and protein levels in MCC-2 and MCC-3 cells following mTOR pathway inhibition, indicating that LDHB and hnRNPF are downstream effectors of mTOR pathway." (PMID 25284964, 2013).
kidney disease (1 paper, 2026). "The public RNA-seq dataset used for validation (GSE299230) is an in vitro HK-2 cell model (hnRNPF overexpression; n = 3 per group) rather than human patient tissue; the small sample size and cellular model limit direct generalizability to complex human kidney disease." (PMID 41481573, 2026).
HNRNPF also shares sentences with these, for which no sentence is quoted: colorectal cancer (2 papers); infection (2); acute myeloid leukemia (1); cervical cancer (1); diabetic nephropathy (1); gastric cancer (1); hypertrophy (1); lymph node metastases (1); mantle cell lymphoma (1); neurodevelopmental disorder (1); prostate adenocarcinoma (1); prostate tumor (1); Reticulocytopenia (1); type 2 diabetes (1).